FBL (fibrillarin rRNA 2'-O-methyltransferase)
Diseases named in the same sentence as FBL in open-access papers (continued):
Sharing a sentence is not in itself a finding about the gene and the disease.
cancer (continued). "It was demonstrated that FBL expression correlates with RNA polymerase I transcriptional activity and production of ribosomal RNA, and is inversely correlated with cancer-cell doubling time." (PMID 32241281, 2020). "Further studies would certainly confirm the qualitative and quantitative role of FBL in human cancer translation and would produce substantial information about identifying the downstream molecular and cellular functions affected by this mechanism." (PMID 32241281, 2020). "While global increases in snoRNAs and FBL activity are tied to cancer development, there are also cases of specific snoRNAs being decreased in cancer." (PMID 32443616, 2020). "Both, FBL and U3 or U8 expression has been shown to be upregulated in several cancer types, indicating their potential involvement in tumorigenesis." (PMID 31026227, 2019). "For instance, overexpression of key rRNA processing factors, such as FBL or dyskerin has been reported in various cancers." (PMID 31026227, 2019). "Enhanced expression of FBL leads to distinct rRNA 2’‐O‐Me modification patterns in cancer cells, producing more heterogeneous ribosomes and thus directly affecting the translational activities of ribosomes, leading to alteration in the translation of specific mRNAs encoding oncogenic proteins." (PMID 40705480, 2025). "Ribosomal proteins RPS3 and RPL4, together with FBL (fibrillarin), contribute to ribosome biogenesis, rRNA processing, and translation, linking this module to the increased protein synthesis demands of rapidly proliferating cancer cells." (PMID 41514860, 2025). "Previous studies identified FBL as a cancer‐promoting factor." (PMID 40705480, 2025). "The mRNA expression of the FBL gene varies across different cancer types." (PMID 40289107, 2025). "FBL-mediated rRNA 2’-O-methylation promotes ribosome biogenesis and translational efficiency; dysregulation of this modification enhances oncogenic protein synthesis and has been increasingly recognized as a driver of cancer progression." (PMID 41568368, 2025). "FBL exerts a dual influence on cancer development through its impact on ribosomal structure and mRNA translation efficiency, as well as its interaction with cancer-related genes to modulate cell cycle progression." (PMID 39605984, 2024). "FBL can affect cell cycle progression by interacting with different cancer related genes." (PMID 39605984, 2024). "FBL also stimulates the homologous recombination-mediated DNA repair in cancer." (PMID 39410048, 2024). "FBL has other well-characterized pathogenic roles involving interactions with classic oncogenes, so its role as a major player in cancer is not unprecedented." (PMID 38474168, 2024). "Ribosome modifications are also of potential interest in this context, and DKC1 and FBL may serve as potential anticancer targets, as shown by the changes in their levels of expression in many cancers." (PMID 34564313, 2021). "Moreover, FBL overexpression has been reported during the differentiation of human stem cells, and in several cancer studies, suggesting a central role in these processes." (PMID 34564313, 2021). "easyCLIP was then used to generate data for 11 additional known RBPs, chosen as representatives (FBL, which associates with C/D-box small nucleolar RNA (snoRNA), and other noncoding RNA (ncRNA), hnRNP C), at random (CELF1, hnRNP D), or for their relevance to cancer (the others)." (PMID 33692367, 2021). "Overexpression of FBL can lead to changes in rRNA methylation patterns, impaired translation fidelity, and increased internal ribosome entry sites (IRES) of key cancer genes." (PMID 39605984, 2024).
cancer (continued). "Amongst these, nucleolin (NCL), fibrillarin (FBL), and nucleophosmin (NPM) are the most studied genes, and their overexpression has been correlated with the poor prognosis of various cancers." (PMID 39410048, 2024). "In this line, NCL, FBL, and NPM are the most studied nucleolar proteins, and their overexpression has been correlated with the poor prognosis of various cancers." (PMID 39410048, 2024). "In the present study, pan-cancer analysis identified PDK4, CCL20, and FBL as central genes (hub genes) with significant differences in expression in 17, 14, and 17 cancer types, respectively." (PMID 38914792, 2024). "It is also notable that we identified over 10 cancer-related genes (including PHGDH, CCND1, IGFBP-2, XAGE1B/E, CYP4F22, RBM11, ORAOV1, MDK, UGT3A5, SSX5, FBL, NKX2) potentially overexpressed in EFT tumors." (PMID 30093970, 2018). "This indicates that PCa cells are dependent on NPM1 and FBL for cancer progression than noncancerous cells." (PMID 40705480, 2025). "Similarly, in AML, FBL supports MYC translation and ribosome biogenesis, with targeted inhibition via CGX-635 reducing cancer cell survival." (PMID 41463151, 2025). "Therefore, CCL20, FBL, and PDK4 emerged as common biomarkers for IS and pan-cancer, crucial for predicting prognosis in patients with both conditions." (PMID 38914792, 2024). "Indeed, overexpression of FBL, another component of box C/D snoRNA/RNP, was observed in multiple cancers and contributed to tumorigenesis through altering translation regulation." (PMID 37891494, 2023). "As FBL plays a role in rRNA production, it is not surprising to find it overexpressed in different cancers." (PMID 30764532, 2019).
tumor (22 papers, 2018 to 2026). "Although FBL has been linked to tumor aggressiveness and metabolic reprogramming, its involvement in hepatocarcinogenesis has not been fully elucidated." (PMID 41568368, 2025). "FBL inhibition reduced migration, invasion, and tumor growth, particularly in SW-480 cells, and altered epithelial–mesenchymal transition markers." (PMID 41463151, 2025). "FBL downregulation impaired migration, invasion, and spheroid growth in SW-480 and SW-620 cells and reduced tumor growth in vivo." (PMID 41463151, 2025). "In vivo, FBL knockdown significantly impaired tumor growth in subcutaneous xenografts, supporting its functional role in CRC progression." (PMID 41463151, 2025). "To sum up, we confirmed that SNORD13H’s tumor-suppressive effects depend on FBL-mediated 2′-O-methylation on rRNA and RAS mRNA." (PMID 40919428, 2025). "In primary CRC samples (D), FBL staining was consistently strong, showing pronounced nucleolar labeling in all tumor cells." (PMID 41463151, 2025). "Tumor analysis revealed even higher FBL expression in metastases than in primary tumors, highlighting its role in metastatic adaptation and survival." (PMID 41463151, 2025). "By demonstrating that FBL expression is elevated in patient-derived metastatic tissues and functionally promotes migration, invasion, and tumor growth, our findings expand the role of ribosome biogenesis factors beyond protein synthesis." (PMID 41463151, 2025). "In conclusion, our study identifies NOP56 as an oncogenic nucleolar protein in HCC that drives tumor progression through interaction with FBL and activation of the PI3K/AKT/CREB pathway." (PMID 41568368, 2025). "Our data revealed that effective FBL depletion in PDXs by lentivirus significantly inhibited tumor growth, along with a significant decrease in Ki67-positive malignant cells in FBL-knockdown tumors, indicating impaired cell proliferation upon FBL depletion." (PMID 40289107, 2025). "To explore the potential role of FBL in HCC tumor growth in vivo, we subcutaneously injected FBL-knockdown and control cells into nude mice." (PMID 40289107, 2025). "Both in vivo and in vitro experiments have shown that reducing the expression of FBL to non-tumor cells can significantly inhibit tumor growth." (PMID 39605984, 2024). "The results showed that the knockdown of FBL significantly inhibited tumor growth and tumorigenesis compared with the control group." (PMID 36004921, 2022). "Collectively, these findings demonstrated that high expression of FBL at protein level in tumor tissues was indicative of poor prognosis of ESCC patients." (PMID 34586744, 2021). "FBL inhibition significantly reduced tumor growth in both SW-480 and SW-620 xenografts." (PMID 41463151, 2025). "This unexpected result suggests that the role of FBL in supporting tumor cell growth may be more pronounced under conditions involving prolonged cell–matrix interactions." (PMID 41463151, 2025). "Notably, tumor volumes and weights in the FBL knockout group exhibited a significant decrease compared to the control group." (PMID 39248163, 2024). "To further characterize the three tumor groups, and particularly to determine how the levels of FBL mRNA from tumor cells diverged from those of healthy cells, we compared FBL mRNA levels quantified in the TTBD series to those of 11 mastectomy samples from healthy donors." (PMID 35545761, 2022). "FBL affects ribosome heterogeneity by regulating ribose methylation of rRNA to regulate translation, and plays an important role in the process of cell proliferation, senescence, tumor genesis and development." (PMID 35464456, 2022). "In histological analysis of tumours, the FBL protein pattern may indicate the use of the rRNA synthesis inhibitor CX-5461." (PMID 32707690, 2020).
tumor (continued). "Consistent with this, FBL depletion restored RAS protein levels and global translational efficiency, proving that SNORD13H’s tumor-suppressive function requires FBL-dependent methylation." (PMID 40919428, 2025). "In conclusion, our study demonstrates that FBL is significantly upregulated in metastatic CRC cells, driving tumor growth, migration, and chemotherapy resistance." (PMID 41463151, 2025). "This study aims to investigate the expression of FBL in human CRC tissues and cell lines and to determine its functional role in tumor progression and metastasis." (PMID 41463151, 2025). "In prostate cancer, FBL enhances the translation of oncogenic mRNAs like IGF-IR, further driving tumor growth." (PMID 41463151, 2025). "Given that FBL downregulation alters EMT-related factors and reduces 3D growth in CRC cells, we investigated its role in tumor progression in vivo." (PMID 41463151, 2025). "Additionally, to assess the prevalence of FBL upregulation in HCC, our investigation was expanded to include 90 paired HCC tumor and adjacent tissues." (PMID 40289107, 2025). "Targeting MYC and FBL could provide a therapeutic approach to reduce CRC tumor growth." (PMID 41463151, 2025). "While our findings demonstrate that FBL promotes tumor aggressiveness and resistance to chemotherapy, they do not explore whether FBL expression varies across key molecular CRC subtypes such as MSI-H, MSS, or RAS/BRAF-mutant tumors." (PMID 41463151, 2025). "Interestingly, FBL mRNA levels significantly discriminated patients with different outcomes exhibiting either small tumor size or no invaded lymph node at early stage diagnosis (P < 0.0001 and 0.0073, respectively)." (PMID 35545761, 2022).
infection (9 papers, 2016 to 2026). The state of being infected such as from the introduction of a foreign agent such as serum, vaccine, antigenic substance or organism. "HeLa cells were transfected with siFBL-2 to knock down endogenous FBL expression, then transfected with a plasmid encoding a FBL gene containing silent mutations in the siFBL-2 target sequence (pCMV2-FBL) followed by infection with HeV." (PMID 27010548, 2016). "The role of FBL in modulating the host microenvironment to support infection will be an interesting subject for future studies." (PMID 27010548, 2016). "Collectively, these results indicate that FBL is required for viral RNA synthesis during the pioneering rounds of infection." (PMID 27010548, 2016). "More importantly, within this single-cycle infection period (12 h p.i.), knockdown of either FBL or EFNB2 significantly reduced intracellular viral RNA levels relative to siNEG." (PMID 27010548, 2016). "Notably, k-means clustering of the ES group PPI network identified three functional modules, with IL6 and FBL emerging as the most prominent hub nodes, suggesting their critical involvement in the host response to polymicrobial infection." (PMID 40771952, 2025). "FBL and M protein interact and co-localize within nucleoli; however, the relevant role(s) of FBL during infection remain unclear." (PMID 40679287, 2025). "This inspired us to investigate the role of FBL in infection and innate immunity." (PMID 35464456, 2022). "FBL knockdown significantly inhibited the VSV protein expression in the early stage of infection." (PMID 35464456, 2022). "Besides, knockdown of FBL significantly inhibited the infection of DNA virus HSV-1 in mouse peritoneal macrophages, in addition to RNA virus VSV." (PMID 35464456, 2022). "Hence, we assessed whether FBL is required for nuclear targeting (import) of M for this stage of the infection cycle." (PMID 27010548, 2016). "Therefore, FBL associates with HeV-M in a nucleolar complex but is not required for M nuclear translocation early during infection." (PMID 27010548, 2016). "The global network notably recognizes six proteins (EPHA2, FBL, PFKM, PSMA5, SSR1, and TFRC) for their involvement in the infection of cells (p: 9.58 × 10− 4)." (PMID 31159726, 2019). "This notion is consistent with our observations that knockdown of FBL does not affect the synthesis of HeV matrix proteins ectopically expressed from a transfected plasmid or the infection and protein synthesis of influenza virus." (PMID 27010548, 2016). "Furthermore, FBL interacts with the nuclear protein SUNA1 to regulate salicylic acid levels and modulate pre-rRNA production, thereby increasing the translation efficiency of specific defense genes in Arabidopsis during infection with the pathogen Pseudomonas syringae (Pst DC3000)." (PMID 39605984, 2024).
bacterial infection (2 papers, 2020 to 2022). "It has been reported that FBL regulates bacterial infection, independent of the p38 MAPK pathway, autophagy, or ubiquitin-proteasome." (PMID 35464456, 2022).
FBL also shares sentences with these, for which no sentence is quoted: colorectal cancer (2 papers); liver fibrosis (2); adrenocortical carcinoma (1); asthma (1); B-cell acute lymphoblastic leukemia (1); bladder urothelial carcinoma (1); chronic hepatitis C (1); Cirrhosis (1); co-infection (1); colorectal tumors (1); dyslipidemia (1); fibrosis (1); Insulin resistance (1); leukemia (1); lung carcinoma (1); memory impairment (1); mesothelioma (1); mycoplasma infection (1); neurodegenerative disease (1); Obesity (1); pancreatic adenocarcinoma (1); rectum adenocarcinoma (1); sarcoma (1); skin cutaneous melanoma (1); squamous cell cervical carcinoma (1); thymoma (1); uterine carcinosarcoma (1); uveal melanoma (1).